ELOVL4 (ELOVL fatty acid elongase 4)
Diseases named in the same sentence as ELOVL4 in open-access papers (continued):
Sharing a sentence is not in itself a finding about the gene and the disease.
Ataxia (continued). "However, a recent report identified an American family with a novel ELOVL4 mutation (c.512T>C,p.I171T) that causes spinocerebellar ataxia with some family members also showing retinitis pigmentosa." (PMID 32780351, 2020). "A systematic literature review was performed by searching databases, including PubMed, ScienceDirect, Web of Science, and SCOPUS, using the terms “SCA34” or “ELOVL4 ataxia”." (PMID 36696030, 2024). "Several different mutations in ELOVL4 cause age-related SCA34 characterized by prominent progressive cerebellar atrophy and ataxia in patients." (PMID 32780351, 2020). "We next identified an individual from another family (Algerian-Maltese-Australian) with the same ELOVL4 variant with spinocerebellar ataxia but without dermatological manifestations." (PMID 36696030, 2024). "This suggests that disease and symptoms associated with mutations in ELOVL4 including neurodegeneration, seizures, intellectual disability, and ataxia, arise primarily from neuronal, rather than glial, dysfunction." (PMID 28507511, 2017). "Based on the findings of the two families and our review of the published literature, we propose that the ELOVL4-associated disease is characterised by a variable phenotypic expression and, importantly, that SCA34 is associated with clinical ataxia phenotypes irrespective of EK skin lesions." (PMID 36696030, 2024). "While SCA34 was prototypically described as familial ataxia with erythrokeratoderma (EK), there have been reports of ELOVL4 variants segregating with ataxia without EK or similar skin lesions." (PMID 36696030, 2024). "The final part of our study creates a convergent framework for the elongase-mediated spinocerebellar ataxias SCA38 (by ELOVL5 p.G230V) and SCA34 (by ELOVL4 p.W246G), demonstrating by direct structural comparison that ELOVL5 G230V and ELOVL4 W246G are position-equivalent pathogenic missense variants." (PMID 37199746, 2023).
autosomal dominant Stargardt-like macular dystrophy (12 papers, 2007 to 2025). "This patient was diagnosed with a mutation in the ELOVL4 gene, which is responsible for autosomal dominant Stargardt-like macular dystrophy." (PMID 37568834, 2023). "Heterozygous inheritance of six different ELOVL4 mutations causes autosomal dominant Stargardt-like macular dystrophy (STGD3), which typically presents with juvenile onset." (PMID 32780351, 2020). "Genetic mutations in ELOVL4 cause Stargardt-3 disease (STGD3)." (PMID 40558564, 2025). "ELOVL4 mutations cause autosomal dominant spinocerebellar ataxia (type 34; SCA34), erythrokeratodermia variabilis (EKV) and autosomal dominant Stargardt-like macular dystrophy (STGD3)." (PMID 33994961, 2021). "The onset of clinical symptoms in PRPH2-associated autosomal dominant Stargardt-like macular dystrophy was reported to start later in life (≥50 years old), which could have allowed to distinguish them from the ABCA4 and ELOVL4 patients." (PMID 34073554, 2021). "In a mouse model of Stargardt disease 3 (STGD3) with conditional KO of Elovl4 in rods and cones, the near complete absence of very long chain fatty acids with nearly normal DHA levels did not lead to photoreceptor loss." (PMID 36978865, 2023).
spinocerebellar ataxia 34 (11 papers, 2017 to 2025). "Spinocerebellar ataxia type 34 (SCA34) is a rare neurodegenerative disorder linked to pathogenic variants in the ELOVL4 gene." (PMID 41445982, 2025). "In the last decade, several different heterozygous point mutations in the Elongation of Very Long Chain Fatty Acids-4 (ELOVL4) have been reported to cause Spinocerebellar Ataxia-34 (SCA34)." (PMID 37568198, 2023). "While some ELOVL4 mutations cause Autosomal Dominant Stargardt-like Macular Dystrophy (STGD3), other ELOVL4 point mutations, such as L168F and W246G, affect the brain and/or skin, leading to Spinocerebellar Ataxia-34 (SCA34) and Erythrokeratodermia variabilis." (PMID 36464075, 2023). "Spinocerebellar ataxia type 34 (SCA34) is an autosomal dominant inherited ataxia due to mutations in ELOVL4, which encodes one of the very long-chain fatty acid elongases." (PMID 34689836, 2021). "Heterozygous inheritance of different ELOVL4 mutations causes Stargardt-like Macular Dystrophy or Spinocerebellar Ataxia type 34." (PMID 28507511, 2017). "Autosomal dominant variants in ELOVL4 cause spinocerebellar ataxia type 34 (SCA34; ATX-ELOVL4), classically associated with a skin condition known as erythrokeratoderma." (PMID 36696030, 2024). "Mutations in ELOVL4 cause three different human diseases with tissue-specific characteristics: Stargardt-like macular dystrophy (STGD3), spinocerebellar ataxia 34 (SCA34), and a neuro-ichthyotic syndrome." (PMID 31616255, 2019). "Heterozygous inheritance of a different set of autosomal dominant ELOVL4 mutations that leads to a full-length protein with single amino acid substitutions causes spinocerebellar ataxia 34 (SCA34), a late-onset neurodegenerative disease characterized by gait ataxia and cerebellar atrophy." (PMID 31616255, 2019). "Spinocerebellar ataxia 34 with or without erythrokeratosis variabilis (EKV) arises from several ELOVL4 variants with single nucleotide polymorphisms in ELOVL4 that generate a full length protein with single amino acid substitutions." (PMID 38850484, 2024). "Mutations in the ELOVL4 gene cause several distinct neurodegenerative diseases including Stargardt-like macular dystrophy (STGD3), spinocerebellar ataxia 34 (SCA34), and a neuro-ichthyotic syndrome with severe seizures and spasticity, as well as erythrokeratitis variabilis (EKV), a skin disorder." (PMID 32780351, 2020).
Macular dystrophy (9 papers, 2010 to 2025). Macular dystrophy is a nonspecific term for retinal degeneration, generally confined to the macula, usually presumed of genetic origin. "Mutations of dominant ELOVL4 are leading to the macular dystrophy of young mice, and ELOVL4 knockout mice would die soon after birth for the lack of skin barrier." (PMID 35912257, 2022). "Heterozygous individuals in ABCA4 disease and control cohort harboring rare variants in macular dystrophy genes CDHR1, CHM, CRX, ELOVL4, PROM1, PRPH2, ROM1." (PMID 35353811, 2022). "Heterozygous individuals in ABCA4 disease and control cohort harboring variants with MAF<0.005 and CADD score >25, in each macular dystrophy gene CDHR1, CHM, CRX, ELOVL4, PROM1, PRPH2, and ROM1." (PMID 35353811, 2022). "Panel-based NGS was performed to identify potentially disease-causing genetic variants in previously identified retinal or macular dystrophy genes, including the five known STGD genes (ABCA4, PROM1, PRPH2, VMD2, and ELOVL4)." (PMID 33988224, 2021). "Because of these many confounders, incomplete penetrance, variable expressivity, unknown family, adoption, consanguinity, early deaths, missed or false diagnosis, the inheritance pattern alone is not sufficient to distinguish between ABCA4-, ELOVL4- and PRPH2-linked macular dystrophies." (PMID 34073554, 2021).
erythrokeratodermia variabilis (8 papers, 2017 to 2023). A rare genetic chronic skin disorder characterized by hyperkeratosis and transient erythema. "In the last decade, a number of different heterozygous mutations in different exons of the ELOVL4 gene have been reported to cause age-related autosomal dominant spinocerebellar ataxia-34 (SCA34) with or without the skin condition erythrokeratodermia variabilis." (PMID 33556440, 2021). "Heterozygous inheritance of several different point mutations in ELOVL4 causes autosomal dominant spinocerebellar ataxia-34 (SCA34) with or without erythrokeratodermia variabilis (EKV, a skin condition)." (PMID 34227061, 2021). "Heterozygous inheritance of other ELOVL4 mutations causes autosomal dominant type 34 spinocerebellar ataxia (SCA34) and/or erythrokeratodermia variabilis (EKV); these patients show no retinal phenotype." (PMID 29168048, 2018). "Several heterozygous mutations in human ELOVL4 have been identified that cause autosomal dominant spinocerebellar ataxia (type 34; SCA34) and/or erythrokeratodermia variabilis (EKV) with no significant retinal phenotype." (PMID 28507511, 2017). "Four different heterozygous mutations in the ELOVL4 gene cause autosomal dominant spinocerebellar ataxia-34 (SCA34), a late-onset degenerative disease of the cerebellum that may present with or without erythrokeratodermia variabilis (EKV; red thickened skin)." (PMID 31616255, 2019).
Intellectual disability (8 papers, 2014 to 2023). "Homozygous mutations in human ELOVL4 cause neurological disorders characterized by seizures, intellectual disability, and neurodegenerative disease." (PMID 28507511, 2017). "These novel ELOVL4 mutations comprise both the heterozygous and homozygous forms, with the latter leading to even more severe human disorders characterized by seizures, intellectual disability, and childhood mortality." (PMID 33556440, 2021). "The neurodevelopmental deficits (intellectual disability, seizures) observed in patients with homozygous inheritance of mutant forms of ELOVL4 support this notion." (PMID 28507511, 2017). "Homozygous deficits in ELOVL4 and its VLC-FA products potentially could contribute to intellectual disability, which is associated with anatomical and physiological deficits in the cortex." (PMID 28507511, 2017).
diabetes (6 papers, 2014 to 2025). "Downregulation of ASM or upregulation of ELOVL4 were protective against diabetes-induced retinal vascular degeneration in cell culture and animal models." (PMID 33581416, 2021). "Taken together, these results demonstrate that genes centrally involved in the regulation of lipid metabolism, srebp1c, PPARγ and PPARα, Elovl4 and Elovl2 have daily rhythms of expression profile in the retina and their daily rhythms are perturbed by diabetes." (PMID 24736612, 2014). "It is known that diabetes reduces the ELOVL4 expression in the retina." (PMID 36291290, 2022). "In their studies, retinal DHA reductions in diabetes were linked to lowered expression of ELOVL2 and ELOVL4, although the mechanism for suppressed expression of these factors remains unclear." (PMID 34425110, 2021). "We propose that combinatorial effects of SFA accumulation because of FAS overactivity with other retinal membrane modifications in diabetes, such as loss of VLC-PUFA because of decreased ELOVL4 or stearyl-CoA desaturase activity, could cause the necessary lipid pathology needed to initiate DR." (PMID 34425110, 2021). "Diabetes also reduces DHA biosynthesis because of downregulation of elongation of VLC fatty acids protein 4 (ELOVL4), whereas ELOV4 overexpression can counteract some of the effects of diabetes on the retina." (PMID 34425110, 2021). "Thus, ELOVL4 and VLC SPL species might have specific roles in vascular abnormalities in diabetes, though further investigation is needed." (PMID 36231042, 2022). "Moreover, ELOVL4 overexpression and VLC ceramide production prevented diabetes-induced BRB breakdown and normalized the TJ structure and function in the diabetic mouse model and inhibited vascular endothelial growth factor-induced permeability in a bovine REC model." (PMID 33581416, 2021).
macular degeneration (6 papers, 2006 to 2023). Loss of vision in the central portion of the retina (macula), secondary to retinal degeneration. "Several mouse models have been generated to investigate the link between disease causing mutations in the Elovl4 gene and macular degeneration that characterizes STGD3 pathophysiology." (PMID 29293603, 2018). "This group included rod specific genes Rbp3, Elovl4, and Abca4, the last two of which have been associated with macular degeneration in humans." (PMID 17044933, 2006). "The R91W;Nrl-/-;Elovl4mut mouse was generated to express a wt and mutant copy of Elovl4, mimicking the autosomal dominant inheritance of STGD3 macular degeneration in all cone PR cells of R91W;Nrl-/- background." (PMID 29293603, 2018). "Mutations in the elongation of very long chain fatty acid 4 (ELOVL4) gene cause Stargardt macular dystrophy 3 (STGD3), a rare, juvenile-onset, autosomal dominant form of macular degeneration." (PMID 29293603, 2018). "The finding that loss of ELOVL4 products results in rapid decline in visual function, RPE atrophy, and photoreceptor death in STGD3 animal models strengthens the relationship between VLC-PUFA and macular degeneration." (PMID 33556440, 2021). "To date, no patients with ELOVL4 variants that developed SCA34 with or without EKV were reported to have macular degeneration as reported in STGD3 patients." (PMID 37568198, 2023). "Thus, we cannot completely rule out the contribution of defective mutant ELOVL4, which lacks VLC-PUFA biosynthesis capability, on the development of macular degeneration in STGD3." (PMID 33556440, 2021).
gastric cancer (5 papers, 2022 to 2025). A primary or metastatic malignant neoplasm involving the stomach. "Recently, the association between ELOVL4 and various tumors such as gastric cancer has been revealed, and the authors advocate further studies to uncover the possible mechanism of ELOVL4 in cancer progression." (PMID 39145825, 2025). "Moreover, in our study, we demonstrated that ELOVL4 is upregulated in gastric cancer tissues and that its high expression is associated with poor survival." (PMID 38817874, 2024). "On the contrary, ELOVL4 is identified as a risk gene in gastric cancer." (PMID 37976136, 2023). "To verify the effects of ELOVEL4 on cell proliferation, migration, and invasion in gastric cancer, we analysed the relative expression levels of ELOVL4 in five GC cell lines (MKN-45, HCG-27, MKN-74, N87, and AGS) and GSE-1 cells." (PMID 38817874, 2024). "High ELOVL4 expression was associated with shorter overall survival (OS) and Disease-Free Survival (DFS) in gastric cancer patients (p < 0.05)." (PMID 38817874, 2024). "Thus, ELOVL4 may be a potential therapeutic target for gastric cancer." (PMID 38817874, 2024). "Finally, the human gastric cancer cell lines, HCG-27 and AGS, were used for in vitro and in vivo experiments, respectively, to further validate the role of ELOVL4." (PMID 38817874, 2024). "ELOVL4, homologous to the ELO family which take part in fatty acid metabolism, has been reported in a gene metabolic signature, which is considered to be correlated with the overall survival (OS) and tumor immune microenvironment (TIME) in gastric cancer." (PMID 36348469, 2022).
psoriasis (5 papers, 2019 to 2024). An autoimmune condition characterized by red, well-delineated plaques with silvery scales that are usually on the extensor surfaces and scalp. "This identified a single nucleotide polymorphism (SNP), rs62407622, located within the ELOVL4 gene that was associated with a strong reduction in ELOVL4, both in primary keratinocytes (P < 2.0 × 10–16) and lesional psoriasis skin (P = 2.1 × 10–2)." (PMID 35900871, 2022). "While the expression level of ELOVL4 was reduced after cytokine treatment in psoriasis-like HPKs compared to normal HPKs, the incubation with GE partly rescued this effect." (PMID 32316273, 2020). "In our psoriasis-like HPKs, GE also increased the ELOVL4 expression." (PMID 32316273, 2020). "Our findings suggest that topical treatment with GE, which partly rescues the ELOVL4 downregulation in psoriasis-like HPKs and increases the CERS3 expression, might contribute to the prevention and/or treatment of psoriasis." (PMID 32316273, 2020). "A psoriasis mouse model showed decreases in the expression of fatty acid elongases ELOVL1, ELOVL3, and ELOVL4 as well as ceramide synthase 3, which are all involved in the synthesis of ceramides exceeding 24 carbons." (PMID 38992724, 2024). "The strong link between ELOVL4 and IL36B, CDK7, CHMP2B, and S100A13 was also evident in RNA-Seq data sets of psoriasis lesional skin." (PMID 35900871, 2022). "Tawada and colleagues also showed that ELOVL4 and ceramide synthase 3 (CERS3) expression is decreased in IFN-γ stimulated keratinocytes and IFN-γ has been shown to be highly expressed in skin lesions of psoriasis patients and might be partially associated with barrier dysfunction in psoriasis." (PMID 32316273, 2020). "The mRNA expression of ELOVL1 and ELOVL4 significantly decreased in AD-like dermatitis, whereas ELOVL1 increased in psoriasis-like dermatitis." (PMID 30838224, 2019). "We incubated normal HPKs and psoriasis-HPKs with GE and determined the CERS3 and ELOVL4 expression." (PMID 32316273, 2020).
hepatocellular carcinoma (4 papers, 2014 to 2025). A malignant tumor that arises from hepatocytes. "ELOVL4 has been shown to be methylated in pancreatic cancer, whereas there is loss of copy number in hepatocellular carcinoma." (PMID 26862848, 2016). "Hypermethylation of ELOVL4 was reported in hepatocellular carcinoma and pancreatic adenocarcinoma by genome-wide methylation analysis." (PMID 24393480, 2014). "ELOVL4 seems to be down-regulated in pancreatic cancer and in hepatocellular carcinoma." (PMID 26862848, 2016). "ELOVL4 is a member of the fatty acid elongation enzyme ELOVL family and is highly methylated in cancers such as hepatocellular carcinoma." (PMID 32843852, 2020).
neuroblastoma (4 papers, 2022 to 2024). Neuroblastoma (NB) is the most common solid, extracranial childhood tumor. "The Elovl4 silencing-dependent decrease of C32:6 and C34:6 fatty acids triggered a reduction of lipid-droplet number in neuroblastoma cells while the accumulation of LD is associated with a better prognosis." (PMID 36056008, 2022). "It has been reported that ELOVL4 serves as a tumor suppressor via the NOTCH-RIPK4-IRF6-ELOVL4 axis in squamous cell carcinoma, and its overexpression is related to the good prognosis for neuroblastoma patients." (PMID 37976136, 2023). "In addition, it has been shown that ELOVL4 promotes the differentiation and healthy accumulation of lipids in neuroblastoma cells but is transcriptionally regulated by the MYCN oncogene, which has severe implications on disease outcomes for neuroblastoma patients." (PMID 37513514, 2023).
retinal disease (4 papers, 2007 to 2025). "As of April 2025, there are no gene-targeted treatments for ELOVL4 or PROM1-related retinal diseases registered on clinicaltials.gov." (PMID 40960229, 2025).
Cerebellar atrophy (3 papers, 2019 to 2021). Cerebellar atrophy is defined as a cerebellum with initially normal structures, in a posterior fossa with normal size, which displays enlarged fissures (interfolial spaces) in comparison to the foliae secondary to loss of tissue. "Here we report the first animal model of SCA34 caused by W246G ELOVL4 mutation that led to age-related impaired synaptic and motor function, prior to the onset of overt neurodegeneration and cerebellar atrophy." (PMID 34227061, 2021).
juvenile macular degeneration (3 papers, 2017 to 2025). "Mutant ELOVL4 causes juvenile macular degeneration in autosomal dominant Stargardt’s disease (STGD3), with loss of central vision, progressive degeneration of the macula and peripheral retina, 22–28, and early functional defects in RPE cells and PRCs29." (PMID 28706274, 2017). "Mutant ELOVL4 causes juvenile macular degeneration and other neurological conditions." (PMID 28706274, 2017).
blinding disorders (2 papers, 2011 to 2021). "A number of laboratories, including ours, carried out a series of in vitro and in vivo experiments aimed at elucidating the biological function of the ELOVL4 protein and how the mutations cause blindness in patients with STGD3." (PMID 33556440, 2021).